CD4 (CD4 molecule)
Diseases named in the same sentence as CD4 in open-access papers (continued):
Sharing a sentence is not in itself a finding about the gene and the disease.
HIV-1 infection (continued). "In line with the DEG enrichment results, the scoring system showed that chronic HIV-1 infection induced upregulation of some essential processes, including response to IFN-α, inflammatory responses, apoptosis, and migration in all CD4+ T cell subsets." (PMID 35351857, 2022). "They observed the upregulation of CXC3R1, ITAC, IGFBP-2, TECK, TRAIL-R4, and MIP-1α in CD4+ and CD8+ T cells and monocytes during the aviremic phase of follow-up, indicating a potential role in viral control during HIV-1 infection." (PMID 35844607, 2022). "Droplet-based scRNA-seq (10× Genomics) and TCR sequencing were performed on CD4+ and CD8+ T cells purified from the PBMCs of 14 individuals with chronic HIV-1 infection, with healthy donors (HD; n = 4) as controls." (PMID 35351857, 2022). "In this study, we show that CD34+CD90+HSC fraction of HSPCs have reduced CD4/CCR5 receptors and increased antiviral restriction factors to limit the HIV-1 infection and demonstrate that they are the potential target cells for CCR5 gene editing." (PMID 35359982, 2022). "Additionally, an interesting observation is that miR-125b expression levels are especially high in resting CD4 + T-cells, which may explain the resistance of these cells to HIV-1 infection in comparison to activated CD4 + T-cells, which present down-regulation of miR-125b." (PMID 36142450, 2022). "In the context of HIV-1 infection, HIV-1-carried CD4+ TSCM cells serve as the source of the virus in HIV-1-infected patients." (PMID 36059484, 2022). "To test the role of CPSF6 in HIV-1 infection of human primary cells, we challenged CPSF6-depleted CD4+ T cells with wild-type and mutant HIV-1." (PMID 35215956, 2022). "Taken together, both CD4+ and CD8+ T cells as well as monocytes were highly activated in CSF during early acute HIV-1 infection." (PMID 34874976, 2021). "Here we introduce a data-validated mathematical model that, to our knowledge, is the first to simultaneously recapitulate viral loads as well as CD4+ and CD8+ T cell subset counts in a macaque model of suppressed HIV-1 infection." (PMID 33432929, 2021). "We found that in patients with HIV-1 infections, there are increased frequencies of PD-1+, CD39+, and PD-1+CD39+ CD8+ T cells, which are inversely correlated with CD4+ T-cell counts and positively correlated with viral load in treatment naïve patients." (PMID 34177939, 2021). "The results show that there was a significant reduction in the proportion of CD73+ memory CD4+ T cells at the earliest stages of primary HIV-1 infection, and a further reduction in subjects with chronic HIV-1 infection." (PMID 33477692, 2021). "In summary, we identified platelet-CD4+ T cell aggregates both in the peripheral blood and lymph nodes of PLWH and revealed significant alterations during HIV-1 infection." (PMID 34987521, 2021). "In summary, we investigated HIV-1 integration site features in resting and activated CD4+ T cells in the context of on and off ART periods and different clinical stages of HIV-1 infection." (PMID 33784259, 2021). "These new observations help define the Env residues critical for HIV-1 infection and demonstrate that Env-defective HIV-1 mutants can rapidly regain replication competency in CD4+ T-cells." (PMID 34935422, 2021). "The ability of RBC viral traps to protect HIV-1 target cells from infection was evaluated by co-culturing control RBCs or CD4-GpA-RBCs with Rev-A3R5 CD4+ T cells, a reporter cell line that expresses luciferase upon HIV-1 infection." (PMID 33723514, 2021). "Of note, co-cultivation of human CD4+ T cell lines with HIV-1-infected uterine epithelial cells (and also by virions released by these cells) led to HIV-1 infection of the CD4+ T cells." (PMID 33467638, 2021). "While our results have implications for the role of platelet-CD4+ T cell aggregates in HIV-1 infection, further studies are needed to establish their potential function in HIV-1 related comorbidities during HIV-1 infection." (PMID 34987521, 2021).
HIV-1 infection (continued). "Gastrointestinal tract CCR5+ CD4+ T cells (GALT) are selectively infected and depleted during acute HIV-1 infection." (PMID 34834213, 2021). "Our study examined the effects of the activation state of CD4+ T cells, ART, and clinical stage of HIV-1 infection on HIV-1 integration site features and selection in longitudinal samples from HIV-1–infected individuals." (PMID 33784259, 2021). "Although many cells die of viral cytotoxic effects during productive HIV-1 infection, a substantial number of HIV-1-infected cells survive and follow the clonal expansion and contraction dynamics of CD4+ T cells." (PMID 34578439, 2021). "A potential explanation for this observation is that a late HIV-1 infection diagnosis and establishment of an effective cART would allow HIV-1 to establish a large latent reservoir in the target cells, especially in CD4 + T cells." (PMID 34873266, 2021). "We examined the influence of the activation state of CD4+ T cells, the effect of antiretroviral therapy (ART), and the clinical stage of HIV-1 infection on HIV-1 integration site features and selection." (PMID 33784259, 2021). "HIV-1 infection-induced upregulation of lncRNA HEAL promotes the transcription of HIV-1 in both Monocytes-derived macrophages and in primary CD4+ T cells." (PMID 34737736, 2021). "In support of this, treatment with the mTOR inhibitors everolimus or rapamycin results in induction of autophagy, leading to a reduction in productive HIV-1 infection of tissue-derived DCs, and a decrease in transmission of HIV-1 by human DCs to CD4+ T-cells." (PMID 33669846, 2021). "Next, to investigate alterations in CD4+ and CD8+ T cell homeostasis within the small and large intestine during HIV-1 infection, we quantified T cells from fresh duodenum, colon, and rectum biopsies in 228 study participants." (PMID 34618690, 2021). "In our study we investigated HIV-1 integration site features in resting and activated CD4+ T cells in the context of on and off ART periods and different clinical stages of HIV-1 infection to better understand how HIV-1 establishes and maintains a reservoir." (PMID 33784259, 2021). "The innate immune activation during early HIV-1 infection may promote HIV-1 replication, as evidenced by the fact that activated DCs can transmit the virus to CD4+ T cells and that the chemokines produced by plasmacytoid DCs (pDC) can recruit susceptible CD4+ T cells to the site of infection." (PMID 33924786, 2021). "In primary human CD4+ T cells and in U87-MG.CD4+CXCR4+ cells transduced to ectopically express huTRIM5α, HIV-1 infection was efficiently inhibited in the presence of IFNα, in a manner dependent on SPRY domain-mediated recognition of the viral capsid." (PMID 33669846, 2021). "We performed WGCNA to assess changes in gene expression profiles in human CD4+ T cells and CD8+ T cells during HIV-1 infection." (PMID 34603402, 2021). "It is likely that HIV-1 infection leads to a modification of the antigen presentation in macrophages and dendritic cell lines, which in turn leads to the anergy of HIV-1-specific CD4+ and CD8+ T cells." (PMID 34835417, 2021). "The physiological relevance of SHREK proteins such as PSGL-1 in restricting HIV-1 virion infectivity has been previously confirmed in HIV-1 infection of primary blood CD4 T cells, and by shRNA knockdown of PSGL-1 in human CD4 T cells." (PMID 34064525, 2021). "Our findings demonstrate that platelet-CD4+ T cell aggregate formation has typical characteristics of HIV-1 permissiveness and is related to immune activation during HIV-1 infection." (PMID 34987521, 2021). "When we analyzed HIV-1 integration sites observed during chronic HIV-1 infection, similar frequencies of HIV-1 integration sites in previously reported clonally expanded cells in activated and resting CD4+ T cells were found (21.2% versus 17.9%, respectively)." (PMID 33784259, 2021).
HIV-1 infection (continued). "In summary, our new observations further define the Env residues critical for HIV-1 infection and demonstrate that Env-defective HIV-1 mutants can rapidly regain replication competency in CD4+ T-cells." (PMID 34935422, 2021). "Although the frequency of HIV-1 infection, as quantified by the frequency of HIV-1 DNA, is lower in CD4+ naive T cells (TN) than in the memory T cell subsets, recent studies have shown that TN harbor a large pool of replication-competent virus." (PMID 33688006, 2021). "On the other hand, CD4+ TSCM cells, in addition to giving rise to different subsets of memory T cells, also constitute reservoirs for HIV-1 infection." (PMID 32097435, 2020). "In the present study, we show that Cul3 is expressed in HIV-1 target cells, such as CD4+ T cells, monocytes, and macrophages and depletion of Cul3 using siRNA or CRISPR/Cas9 increases HIV-1 infection in immortalized cells and primary CD4+ T cells." (PMID 32882949, 2020). "Hu-DRAG mice are capable of supporting HIV-1 infections when challenged intravaginally as the mucosa of the FRT and gut both repopulate with CD4+ T cells and TFH cells." (PMID 33746940, 2020). "The isolated immune cells were exposed to the same HIV conditions as the tissue biopsies and we assessed HIV-1 infection in DC, CD163+ macrophages and CD4+ T cells, which should represent the immune cells susceptible to HIV-1 infection." (PMID 32876566, 2020). "Furthermore, the impact of HIV-1 infection on the function of CD4+ CD161+ T cells is unknown." (PMID 33322496, 2020). "Given the decrease of CD4+DPP4+ T cells in progressive HIV-1 infection, we assessed the correlation of DPP4+CD4+ T cells with markers of disease progression." (PMID 32946499, 2020). "Upregulation of PVR can occur on CD4+ T cells in HIV-1 infection, especially on lymph node TFH CD4+ T cells, which are the major site of HIV-1 reservoir concentration." (PMID 32432050, 2020). "To analyze the impact of HIV-1 infection on IFNα signaling, we determined the surface expression of IFNAR2 on NK cells, B cells, CD4+ and CD8+ T cells among LPMCs isolated from the gastrointestinal mucosa of 11 healthy donors, undergoing abdominal surgery." (PMID 31935222, 2020). "Maraviroc is a drug for human immunodeficiency virus type 1 (HIV-1) infection and it shows effect of inhibiting HIV-1 entry by blocking CCR5 on the CD4+ T-cells)." (PMID 32727125, 2020). "The longitudinal pattern over acute HIV-1 infection reveals changes in the subset composition as compared to the pre-infection time point, with relatively fewer CD8+ and CD4+ MAIT cells, and an expanding DN MAIT cell subset." (PMID 31937782, 2020). "In HIV-1 infection, the viral accessory proteins Vpu and Nef have been shown to antagonize PSGL-1 on CD4 T cells through surface downregulation and intracellular degradation." (PMID 33396594, 2020). "Therefore, we postulate that therapeutics that mimic viral target cells could prevent escape and permanently control HIV-1 infection by exposing a universal vulnerability—the requirement to bind clusters of CD4 on a target cell—that is potentially inherent to all HIV-1 strains and variants." (PMID 32690692, 2020). "Therefore, primary CD4 T cells are activated artificially before the HIV-1 infection in studies in vitro; however, such stimulation may affect the cellular transcriptome, proteome, epigenome, and interactome, and introduce significant bias into results of the experiment." (PMID 32625189, 2020). "In purified activated CD4+ T cells, IFN-λ3 pretreatment leads to antiviral ISG induction and a significant decrease in HIV-1 infection." (PMID 32353085, 2020). "CD4+ T cells treated with either IFN-λ3 or IFN-α2 had significantly decreased HIV-1 p24 positive cells, indicating IFN-λR or IFN-αR signaling inhibited HIV-1 infection." (PMID 32353085, 2020). "The capacity of CD161+ CD4+ T cells to produce IFNγ, TNF, and IL-17 was decreased post-HIV-1 infection compared to pre-infection." (PMID 33322496, 2020).
HIV-1 infection (continued). "Possibly this is due to the strong reduction of CD8+DPP4+ T cell percentages in HIV-1 infection, which was more pronounced for CD8+ T cells than for CD4+ T cells." (PMID 32946499, 2020). "We used CD3+CD4+CD45RO+CCR7+ central memory T cells (CMT) for HIV-1 infection and culture in the presence of CCL19 to establish HIV latent infection." (PMID 32792548, 2020). "After we verified that Cul3 is expressed in cells of the human immune system that are relevant for HIV-1 infection, we next sought to investigate the effect of Cul3 on HIV-1 replication in infected primary CD4+ T cells." (PMID 32882949, 2020). "Together, these data indicate that CD4+ T-cells are the primary target cells in SIV and HIV-1 infections." (PMID 32992787, 2020). "Our work demonstrated that PSGL-1 is a key mediator of IFN-γ’s antiviral activity in human CD4+ T cells, the mechanism of which would therefore be important for the understanding of IFN-γ’s role in the defense against HIV-1 infection." (PMID 32802403, 2020). "The underlying lamina propria is populated with high populations of lymphocytes and macrophages, which express CD4 in combination with the coreceptor C-C chemokine receptor type 5 (CCR5) and serve as targets for HIV-1 infection." (PMID 31866988, 2019). "A significant CD4 + T-cell decline and increased CD8 + T-cell numbers were observed as a consequence of sustained HIV-1 infection." (PMID 31266936, 2019). "In particular, age nadir CD4+ T cell count, low CD4/CD8 T cell ratio, duration of HIV-1 infection, CD4 and CD8 T cell activation, inflammation and microbial translocation have been associated with a failure of immune recovery (reviewed in 2)." (PMID 31869342, 2019). "It is desirable to transduce activated CD4+ T cells, the natural targets of HIV-1 infection, and CD34+ HSPCs, which can differentiate to form new CD4+ T cells." (PMID 31778955, 2019). "During HIV-1 infection, the latent reservoir of integrated but inducible HIV-1 predominantly takes place in resting central-memory T (TCM) lymphocytes CD4 and in few monocytes/macrophages." (PMID 31095640, 2019). "Productive HIV-1 infection results in a Vpr-mediated depletion of CTIP2 in microglial cells and CD4+ T cells, two of the major viral reservoirs." (PMID 31511615, 2019). "HIV-1 infection triggers inflammasome induction, in particular activation of the NLRP3 inflammasome, in various cell types including monocytes, macrophages and CD4+ T cells." (PMID 31426525, 2019). "The frequency of Foxp3+Helios+CD45RA+ Treg cells was inversely correlated with CD4 T-cell counts and CD4/CD8 ratio during acute and chronic HIV-1 infection." (PMID 31651258, 2019). "Robust, broadly cross-reactive and polyfunctional virus-specific responses of both CD4+ and CD8+ T-cells have been shown to distinguish HIV-2 from HIV-1 infections." (PMID 31484562, 2019). "To further confirm the role of MALAT1 in HIV-1 infection, we overexpressed it by transfecting the pcDNA3.1/MALAT1 into PHA-P-activated primary CD4+ T cells, and then infected these cells with HIV-Luc/NL4-3." (PMID 30788509, 2019). "Here we report that a subset of CD4+ T cells, characterized by CD161 expression on the surface, is highly permissive for HIV-1 infection." (PMID 31594817, 2019). "Here, we report that plasma levels of CCL18 are significantly increased during HIV-1 infection and negatively correlate with CD3+CD4+ T cell counts in patients on combination antiretroviral therapy (cART) with a suppressed viral load." (PMID 30979916, 2019). "The GALT is a major reservoir for CD4+CCR5+ memory T-cells and approximately 80% of these cells are lost in the first weeks following HIV-1 infection." (PMID 31487324, 2019). "During primary HIV-1 infection, CXCL10 plasma levels predict disease progression even better than plasma viral loads or CD4 +T cell counts." (PMID 30717826, 2019).
HIV-1 infection (continued). "Taken together, these data suggest that although all three TH2 chemokines are increased during HIV-1 infection, only CCL18 and/or CCL18-producing cells play a role in CD4+ T cell recovery as experienced by some HIV-1-infected patients undergoing cART." (PMID 30979916, 2019). "Previous reports suggested that specific targeting of CCR5 in human autologous CD4+ T cells by ZFN, TALEN or CRISPR/SpCas9 protected against HIV-1 infection." (PMID 31186067, 2019). "Activation of CD4+ T cells enhances APOBEC3G expression and recruitment into HMM, rendering the cells permissive to HIV-1 infection." (PMID 31708924, 2019). "One possibility is that while HIV-1 infection impairs CD4+ T cell memory formation, this is incompletely abrogated and a small number of cells infected early in untreated infection may become long-lived memory CD4+ T cells despite profound dysregulation in IL-7 signaling at the population level." (PMID 31507594, 2019). "On the contrary, in the case of mDCs, productive HIV-1 infection decreased expression of interferon-stimulated genes CXCR3-binding chemokines, suggesting a diminished trans-infection of CD4 lymphocytes." (PMID 31708924, 2019). "HIV-1 infection creates multiple challenges for CD4+ T cell homeostasis, most obviously reflected in the absolute loss of CD4+ T cells in untreated infection The cytopathic effects of direct CD4+ T cell infection alone do not explain this loss of CD4+ T cells, suggesting indirect mechanisms." (PMID 31507594, 2019). "- Memory CD4+ T cells which mostly express the IL-7 receptor (IL-7R) α chain, CD127 are profoundly depleted during untreated HIV-1 infection." (PMID 31507594, 2019). "Beyond the CD4+ T cell decrease, one of the characteristics of HIV-1 infection is CD8+ T cell increase, resulting in a lower CD4/CD8 ratio and CD4% over time." (PMID 30050532, 2018). "During primary HIV-1 infection (PHI), viral loads can reach values higher than one million HIV-1 RNA copies/mL, and a significant decrease in CD4+ T cell counts occurs." (PMID 30541557, 2018). "Our study reveals the CD4+ ILC1 population as a new target for HIV-1 infection and identifies an IFN-I mediated mechanism of ILC1 depletion during chronic HIV-1 infection." (PMID 29304123, 2018). "One such study tested an array of TALENs designed to target the CCR5 gene by transfecting human primary CD4+T cells and GHOST-CCR5-CXCR4 (a reporter cell line for HIV-1 infection)." (PMID 30619107, 2018). "Interestingly, HIV-1 infection-induced activation of macrophages, in turn, leads to upregulation of inhibitory receptor (IR) expression and reduced effector function of co-cultured autologous CD4+ and CD8+ T cells, and the phenotype is suppressed upon antagonism of IFN-I." (PMID 30150664, 2018). "To interrogate the role of endogenous IFITMs, we knocked down IFITMs in human PBMCs and purified CD4+ T cells and determined the contribution of IFITMs in IFN-mediated inhibition of multiple and single round of HIV-1 infection." (PMID 30087232, 2018). "Altogether, these results show that HIV-1 infection triggers HIF-1α activity in vitro, promoting T cell glycolytic activity, and that CD4+ T cells from HIV-1-infected patients have higher HIF-1α protein levels than those from HIV-negative healthy individuals." (PMID 30206166, 2018). "It has been shown that HIV-1 infection impairs B and T lymphocyte attenuator (BTLA)-mediated signaling in CD4+ and CD8+ cells dependent on pDC-derived IFN-α, which contributes to broad T-cell hyperactivation." (PMID 29597250, 2018). "The median duration of HIV-1 infection in the combined cohort was 17 years (IQR: 13–22), median CD4 T-lymphocyte count 329 cells/mm3 (IQR: 217–388), and median CD4 nadir 21 cells/mm3 (IQR: 2–60)." (PMID 28328546, 2017). "The common γc cytokines were reported to robustly enhance the Tim-3 expression on CD4+ and CD8+ T cells in HIV-1 infection." (PMID 28401068, 2017).